IL7 (interleukin 7)
Diseases named in the same sentence as IL7 in open-access papers (continued):
Sharing a sentence is not in itself a finding about the gene and the disease.
ovarian carcinoma (16 papers, 2013 to 2025). A malignant neoplasm originating from the surface ovarian epithelium. "LAMC3 is linked to drug resistance in ovarian cancer, while IL-7 exerts potent immunomodulatory effects and can act on tumor cells to exert anti-tumor activity." (PMID 41179658, 2025). "Similarly, in ovarian cancer, increased IL-7 levels have been linked to disease progression and poor clinical outcomes." (PMID 39334861, 2024). "In this study, we elucidated the role of the IL-7/IL-7R axis in the ovarian cancer microenvironment and identified IL-7R expression in tumor cells as a critical target for the regulation of IL-7 signaling." (PMID 41360767, 2025). "Subsequently, this study measured the concentrations of IL-7 in the plasma and ascites of ovarian cancer patients, and compared them with the concentrations of IL-7 in the plasma and peritoneal lavage fluid of patients with benign ovarian tumors." (PMID 41360767, 2025). "Three interleukins have been studied a little more in-depth, namely IL-7, IL-8 and IL-12 in the context of liposomal delivery and ovarian cancer." (PMID 37612696, 2023). "The top significant Reactome pathways using the SCZ and ovarian cancer-related special genes and the histone deacetylation pathway include deubiquitination and interleukin-7 signaling." (PMID 36138824, 2022). "Since high IL-7 serum levels have been detected in ovarian cancers, it has been suggested that IL-7 can be used in combination with CA-125 to distinguish between malignant and benign ovarian tumours." (PMID 29554938, 2018). "A cytokine that has been investigated in the context of ovarian cancer detection is IL-7 (interleukin 7)." (PMID 29554938, 2018). "In this case, other tumour/immune biomarkers need to be used in combination with CA-125/IL-7, to increase the specificity towards ovarian cancers, or towards other cancers." (PMID 29554938, 2018). "Here we use a computational approach to investigate the effect of combining multiple biomarkers for ovarian cancer (e.g., CA-125 and IL-7), to improve early cancer detection." (PMID 29554938, 2018). "Another restriction of this study is related to the multifaceted role of IL-7: on boosting the immune response, and on the possibility of IL-7 to act as a growth factor for ovarian cancer cells." (PMID 29554938, 2018). "However, the present study documents an opposing effect in ovarian cancer: endogenous IL-7/IL-7R signaling promotes disease progression by driving tumor cell-autonomous proliferation and the formation of an immunosuppressive microenvironment." (PMID 41360767, 2025). "Currently, the specific mechanisms underlying the functions of IL-7 and its receptor (IL7R) in the ovarian cancer TME remain unclear." (PMID 41360767, 2025). "This discrepancy suggests that serum IL-7 in ovarian cancer patients may originate from other cell types within the tumor microenvironment (TME; e.g., immune cells or stromal cells) or be indirectly produced via systemic inflammatory responses." (PMID 41360767, 2025). "Finally, we discuss our results in the context of diagnosing ovarian cancer in the (IL-7, CA-125) variables space." (PMID 29554938, 2018). "Additionally, IL7R was stably expressed across four human ovarian cancer cell lines, indicating that these cells may be responsive to circulating IL-7." (PMID 41360767, 2025). "We observed the association of SUCNR1 expression with interleukins, including IL1B (cor = 0.473, p = 2.86e-18), IL7 (cor = 0.39, p = 1.78e-12), IL16 (cor = 0.508, p = 2.66e-21), and IL18 (cor = 0.348, p = 4.67e-10), in ovarian cancer." (PMID 33062639, 2020). "The second one, cited earlier, is a phase I clinical trial (NCT03932565) using fourth-generation CAR-T cells coproducing IL-7 and CCL19/IL-2 in patients with Nectin4-positive advanced malignant solid tumors such as NSCLC, breast, bladder, pancreatic and ovarian cancer." (PMID 35211124, 2022).
ovarian carcinoma (continued). "After 21 days of induction with SFTG36 (SCF, FLt-3L, TPO, GM-CSF, IL-3 and IL-6), IS721 (IGF-1, SIS3, IL-7 and IL-21) and IL-15/Hsp70 media, NK cells phenotypes were studied and their cytotoxicity against K562 human erythroleukemia cells and SKOV3 ovarian carcinoma cells was analyzed." (PMID 34098947, 2021). "Notably, the primary source of IL-7 in ovarian cancer may be the systemic circulation rather than the tumor microenvironment itself, which further amplifies the dominance of IL-7R-positive tumor cells in regulating the microenvironment." (PMID 41360767, 2025).
acute lymphoblastic leukemia (15 papers, 2013 to 2025). Leukemia with an acute onset, characterized by the presence of lymphoblasts in the bone marrow and the peripheral blood. "IL-7 has been shown to induce GCs resistance in vitro in a subset of samples from patients with acute lymphoblastic leukemia." (PMID 35252347, 2022). "Moreover, it was demonstrated in patient-derived xenograft (PDX) models that T-cell acute lymphoblastic leukemia (T-ALL) cells developed more slowly when engrafted in IL-7-deficient mice compared to mice expressing IL-7." (PMID 34066732, 2021). "When transduced with retroviral vectors encoding the Bcr-Abl kinase, the IL7-dependence of these cells is abrogated, and they initiate acute lymphoblastic leukemia (ALL) when infused intravenously into unconditioned, syngeneic wild type (WT, Arf+/+) recipient mice." (PMID 30815226, 2019). "Furthermore, p27kip1 has been shown to play a crucial role in the homeostatic proliferation induced by IL-7 on T cells and T-cell acute lymphoblastic leukemia cells." (PMID 26110906, 2015). "The reverse may occur as well; rapamycin inhibits proliferation and induces apoptosis of pre-B acute lymphoblastic leukemia and these effects are abrogated by IL7." (PMID 26566388, 2015). "IL-7 was evidence to promote cell viability, cell cycle progression, and growth of T-cell acute lymphoblastic leukemia (T-ALL) in vitro." (PMID 36389666, 2022). "IL-7 rescues rapamycin-induced apoptosis of B-cell precursor acute lymphoblastic leukemia-acute lymphoblastic leukemia (ALL) cells by upregulating MEK/ERK." (PMID 36142322, 2022). "For example, the importance of JAK/STAT in early T-cell precursor (ETP) acute lymphoblastic leukemia (ALL) has been confirmed when the JAK1/2 inhibitor ruxolitinib has been used in murine xenograft models leading to abrogation of the STAT5 activation in response to IL-7." (PMID 34055801, 2021). "Interleukin 7 (IL-7) is a critical cytokine that plays a fundamental role in B- and T-cell development and in acute lymphoblastic leukemia (ALL)." (PMID 31817502, 2019). "In vitro studies have shown that the IL7R in t-line acute lymphoblastic leukemia (T-ALL) mediates T-ALL cell proliferation and survival after binding to IL7 secreted by bone marrow and thymic stromal cells." (PMID 37381714, 2023). "IL-7 also activates STAT1 and STAT3 which promote B cell precursor acute lymphoblastic leukemia proliferation and survival of B cell progenitors, respectively." (PMID 36142322, 2022). "This regulation has also been demonstrated in T-cell acute lymphoblastic leukemia (T-ALL) where interleukin-7 (IL-7) enhances NOX and mitochondrial complex I activity, thus contributing to elevated ROS in T-ALL cells." (PMID 29868481, 2018). "For instance, the distances between the C-terminal of mutated IL-7Rα homodimer in T cell and B cell in acute lymphocytic leukemia (ALL) patients are less than 30 Å, which spontaneously activate the IL-7 signaling pathway to malignant proliferation of lymphocyte in absence of IL-7." (PMID 28127156, 2017).
atherosclerosis (15 papers, 2011 to 2025). A disease characterized by the build-up of fatty material and calcium deposition in the arterial wall resulting in partial or complete occlusion of the arterial lumen. "Thymic stromal lymphopoietin (TSLP), a distant paralog of the cytokine IL-7, has been shown to be associated with atherosclerosis." (PMID 35321112, 2022). "Further, it was found that patients with generalized atherosclerosis, in addition to a statistically significant increase in T-regulatory lymphocytes, TGFβ and IL7, also had a significant decrease in concentrations of IL6 and IL8." (PMID 37569579, 2023). "An important immune regulatory cytokine, IL-7, was also elevated in patients with severe atherosclerosis." (PMID 33854919, 2020). "Due to the fact that the peritoneal cavity is the main residence of B1 cells we decided to transfer IL-7, IL-33-expanded ILC2s intraperitoneally to apoE−/− mice and study the induced immunological response as well as their effect on atherosclerosis." (PMID 31823769, 2019). "Persistent low-grade inflammation, characterized by moderate increases in circulating pro-inflammatory cytokines (C-reactive protein: CRP; interleukins (IL): IL-6, IL-2, IL-7, IL-8, etc.), plays a significant role in all atherosclerosis formation and progression phases." (PMID 40428891, 2025). "IL-7 is also hypothesized to be a key regulator in atherosclerosis through its receptor (IL-7r) and through artery tertiary lymphoid organs (ATLOs)." (PMID 34206780, 2021). "In summary, IL-7 had a dual effect on coronary atherosclerotic disease, which could promote the formation of atherosclerosis by activating monocytes/macrophages and platelets, etc., and could also upregulate the level of Tim-3 in CD4+ T cells in peripheral blood of patients with CHD." (PMID 34236813, 2022). "Whether IL-7 and IL-15 have a role in atherosclerosis is less well established." (PMID 32647892, 2021). "Surprisingly, some markers of atherosclerosis (fractalkine/CX3CL1, CCL8, M-CSF, HGF), T-cell development/activation (CD40L, IL-7, CCL25, IL-2RB, IL-15RA, CD6) and angiogenesis (VEGF-A) were significantly increased only in AD." (PMID 28821884, 2017).
hepatocellular carcinoma (14 papers, 2016 to 2025). A malignant tumor that arises from hepatocytes. "Additionally, these results imply that autocrine and paracrine IL-7 may activate intracellular signaling pathways and associated molecules in hepatoma cells via interacting with increased IL-7R mediated by HBX." (PMID 27821177, 2016). "Stimulation of these primary HLSECs with both type I or II IFN resulted in a significant induction and secretion of IL-7, comparable to that of hepatoma cell lines." (PMID 33584648, 2020). "Taken together, our results suggest that increased IL-7R is involved in HBX-mediated proliferation and migration of hepatoma cells, and that activation of IL-7R mainly depends on its interaction with IL-7." (PMID 27821177, 2016). "This suggests that in the hepatoma microenvironment, IL-7, secreted by the tumor, as well as by other types of cells, contributes to the abnormal activation of IL-7R in hepatoma cells." (PMID 27821177, 2016). "Additionally, exogenous IL-7 stimulation substantially enhanced the proliferation and migration of hepatoma cells." (PMID 27821177, 2016). "IL7 and MAL2 promote Sorafenib resistance in hepatocellular carcinoma by enhancing JAK/STAT and PI3K/AKT signaling, while autophagy-inducing stapled peptides counteract this resistance by degrading resistance-related proteins and synergizing with Sorafenib." (PMID 39315094, 2024). "Similarly, IL7 was found to increase proliferation of circulating CD4 and CD8 T-cells leading to reduced flank tumor growth in a hepatocellular carcinoma model." (PMID 38554147, 2024). "After treatment with IL-7R shRNA, the proliferation and migration of hepatoma cells, with or without exogenous IL-7 stimulation, were significantly decreased." (PMID 27821177, 2016). "NCT03198546 is a phase 1 trial testing the safety and efficacy of anti-GPC3-7 × 19 CAR-T cells (GPC3 CAR-T cells to secrete human IL-7 and CCL19) in patients with advanced hepatocellular carcinoma (HCC) expressing GPC3." (PMID 37371075, 2023). "studied, in vitro and in vivo, the ability of GPC3 (Glypican 3 protein)-targeted CAR-T cells co-expressing IL-7 and the PH20 hyaluronidase to infiltrate hepatocellular carcinoma (HCC) xenograft models." (PMID 35211124, 2022).
multiple myeloma (14 papers, 2006 to 2025). "This group has further shown a role for IL-7 in the suppressed osteoblast formation and differentiation induced by multiple myeloma cells from human patients." (PMID 24278766, 2013). "Some investigators have concluded that the leukocytosis is in response to the myeloma because monoclonal B-cell clones in myeloma can produce cytokines which are able to activate stromal cells to produce IL-6, IL-7, and IL-11 to stimulate T lymphocytes to produce IL-3 and GM-CSF." (PMID 25143840, 2014). "Compared with IL-2 or IL-7, IL-15 was found to increase the persistence and efficacy of CAR T cells in multiple myeloma." (PMID 36618357, 2022). "The first observation in multiple myeloma is that MM-EVs are able to carry several pro- and anti-inflammatory cytokine and chemokines, i.e., IL-6, CCL2, IL-15, IL-7, IL-32, IL-10 and IL-16, and VEGF." (PMID 31266187, 2019). "Some cytokines such as IL-7, IL-3, IL-6, TNF-α produced by myeloma cells can inhibit the differentiation and activativity of osteoblasts and induce osteoblasts apoptosis." (PMID 25788856, 2014). "Human myeloma cells have been reported to stimulate RANKL production by T cells, by a mechanism involving IL-7 and/or IL-6." (PMID 24278766, 2013). "Via systematic optimization, we generated BC-7×21 TRuC-T cells secreting IL-7 and CCL21 that could robustly eliminate multiple myeloma cells in vitro and in vivo." (PMID 39776916, 2024). "BCMA/CS1 bispecific TRuC-T cells secreting IL-7 and CCL21 may represent a novel therapy for relapsed/refractory multiple myeloma." (PMID 39776916, 2024). "The miR-21 passenger strand (miR-21-3p), along with miR-103a-3p and miR-181a-3p involved in OB or OC’ differentiation, have been found in EVs shed by the myeloma RPMI8226 cell line together with protein regulators of bone lesions such as DKK-1, IL-7, and sFRP2 (secreted Frizzled Related Protein 2)." (PMID 31266187, 2019). "Moreover, our group have reported that BCMA or CD19 CAR-T cells expressing IL-7 and CCL19 may represent a promising therapy for relapsed/refractory multiple myeloma or B cell malignancies." (PMID 39776916, 2024).
pneumonia (14 papers, 2011 to 2025). An acute, acute and chronic, or chronic inflammation focally or diffusely affecting the lung parenchyma, caused by an infection in one or both of the lungs (by bacteria, viruses, fungi, or mycoplasma.). "In lung resection surgery patients, post-operative pneumonia was associated with a perioperative decrease in IL-2 mRNA (P < 0.0001) and IL-7 mRNA (P = 0.003)." (PMID 21711552, 2011). "PICFLU - The adjusted BS4 module containing EGF, Eotaxin, FGF-2, Fractalkine (FKN), GRO, IFN-α2, IL-12-P70, IL-7, MDC, and sCD40-L was negatively associated with shock, pneumonia-ARDS and ECMO or death (odds ratio 0.463, 0.598, 0.494, FWER-p = 0.0002, 0.0155, 0.0283, respectively)." (PMID 31275311, 2019). "Pneumonia correlates with specific cytokines IFN2, Il-15, IL-7, sCD40L, MCP-1, FGF-2, MIP-1b, MIP-1a, MDC, and GM-CSF." (PMID 37629267, 2023). "Significantly higher plasma levels of IL-2, IL-7, IL-10, G-CSF, IP-10, MCP-1, MIP-1α, and TNFα were found in patients with severe pneumonia developing ARDS and requiring ICU admission and oxygen therapy compared to non-ICU patients showing pneumonia without ADRS." (PMID 33362782, 2020). "Significantly higher plasma levels of IL-2, IL-7, IL-10, G-CSF, IP-10, MCP-1, MIP-1α, and TNFα were found in patients with severe pneumonia developing ARDS compared to non-ICU patients showing pneumonia without ADRS." (PMID 34578468, 2021). "Notably, significantly higher plasma levels of IL-2, IL-7, IL-10, G-CSF, IP-10, MCP-1, MIP-1α, and TNFα were found in patients with severe pneumonia developing ARDS and required ICU admission and oxygen therapy compared to non-ICU patients showing pneumonia without ADRS." (PMID 34639132, 2021).
psoriasis (14 papers, 2012 to 2025). An autoimmune condition characterized by red, well-delineated plaques with silvery scales that are usually on the extensor surfaces and scalp. "It is worth mentioning that, from this analysis, IL-7 emerges as nodal cytokine in the serum correlated with multiple metabolites in psoriasis patients and with proline in healthy subjects." (PMID 34006909, 2021). "Several studies demonstrated an increase in IL-7 in psoriasis." (PMID 37049538, 2023). "A previous study demonstrated that IL-7 signaling blockade using anti-IL-7Rα monoclonal antibody (mAb) treatment or endothelial-specific deletion of IL-7Rα attenuates psoriasis-like skin inflammation mediated by infiltration of T cells and DCs into the inflamed lesion." (PMID 37373104, 2023). "IL-7, therefore, emerges as a relevant cytokine at systemic level in psoriasis patients and a node that may link with metabolites pathways." (PMID 34006909, 2021). "Interestingly, several studies have previously reported that IL-7 levels were increased in psoriatic skin and/or in the plasma of psoriasis patients." (PMID 31406267, 2019). "Since edema formation is one of the cardinal signs of inflammation and our previous findings had demonstrated that the IL-7/IL-7Rα axis supports lymphatic drainage, we here set out to further investigate the overall role of IL-7Rα signaling in psoriasis-like skin inflammation." (PMID 31406267, 2019). "The bidirectional association between OSA and psoriasis suggests a common systemic inflammatory pathway The activity of IL-7, TNF, IL-6, and C-reactive protein was significantly increased in OSA patients, and the increase of this activity was also significantly correlated with psoriasis." (PMID 40166062, 2025). "Indeed, we identified a major cluster of correlation comprising Ac, Asn and Gly showing positive (Ac) and negative correlation (Asn and Gly) with key cytokine of the psoriasis pathology, such as IL-17, IFN-γ, IL-2, as well as with IL-7 and FGF." (PMID 34006909, 2021). "Thus, although the current literature would suggest a more prevalent role for IL-7 thanks to its Th1- and Th17- promoting activity, a potential contribution of TSLP to psoriasis-like skin cannot be ruled out at present." (PMID 31406267, 2019).